DNMT3L (DNA methyltransferase 3 like)
Description:
Catalytically inactive regulatory factor of DNA methyltransferases that can either promote or inhibit DNA methylation depending on the context (By similarity). Essential for the function of DNMT3A and DNMT3B: activates DNMT3A and DNMT3B by binding to their catalytic domain. Acts by accelerating the binding of DNA and S-adenosyl-L-methionine (AdoMet) to the methyltransferases and dissociates from the complex after DNA binding to the methyltransferases. Recognizes unmethylated histone H3 lysine 4 (H3K4me0) and induces de novo DNA methylation by recruitment or activation of DNMT3. Plays a key role in embryonic stem cells and germ cells (By similarity). In germ cells, required for the methylation of imprinted loci together with DNMT3A (By similarity). In male germ cells, specifically required to methylate retrotransposons, preventing their mobilization (By similarity). Plays a key role in embryonic stem cells (ESCs) by acting both as an positive and negative regulator of DNA methylation (By similarity). While it promotes DNA methylation of housekeeping genes together with DNMT3A and DNMT3B, it also acts as an inhibitor of DNA methylation at the promoter of bivalent genes (By similarity). Interacts with the EZH2 component of the PRC2/EED-EZH2 complex, preventing interaction of DNMT3A and DNMT3B with the PRC2/EED-EZH2 complex, leading to maintain low methylation levels at the promoters of bivalent genes (By similarity). Promotes differentiation of ESCs into primordial germ cells by inhibiting DNA methylation at the promoter of RHOX5, thereby activating its expression (By similarity).
Synonyms: MGC1090
Tractability: Small molecule: a structure with a bound ligand is known; a high-quality ligand is known; it has a binding pocket of medium quality.
Gene: Protein-coding gene on chromosome 21 (44,246,339 to 44,262,216, reverse strand). Ensembl gene ENSG00000142182.
Subcellular location: Nucleus
Subcellular location (Human Protein Atlas): Nuclear speckles
Pathways (Reactome):
Gene expression (Transcription): DNA methylation; Regulation of endogenous retroelements by Piwi-interacting RNAs (piRNAs)
Gene Ontology:
Molecular function: enzyme activator activity; enzyme binding; protein binding
Biological process: negative regulation of gene expression, epigenetic; DNA methylation-dependent constitutive heterochromatin formation; genomic imprinting; male meiosis I; negative regulation of DNA methylation-dependent heterochromatin formation; negative regulation of DNA-templated transcription; spermatogenesis; stem cell differentiation; transposable element silencing by heterochromatin formation; regulation of gene expression; transposable element silencing by piRNA-mediated DNA methylation
Cellular component: catalytic complex; cytosol; nucleus; cytoplasm; ESC/E(Z) complex; condensed nuclear chromosome; heterochromatin
Genetic constraint (gnomAD): Loss-of-function variants: 33 observed, 37.42 expected, observed/expected ratio (o/e) 0.88, 90% interval 0.67 to 1.18. The upper end of that interval is the gene's LOEUF score, 1.18, which puts it in group 5 of 6, group 1 being the genes least tolerant of losing a copy. Missense variants: 310 observed, 317.33 expected, observed/expected ratio (o/e) 0.98, 90% interval 0.89 to 1.07. Synonymous variants: 117 observed, 126.63 expected, observed/expected ratio (o/e) 0.92, 90% interval 0.79 to 1.08.
Homologues: Orthologues: chimpanzee DNMT3L (99% identical), macaque DNMT3L (94% identical), pig DNMT3L (75% identical), dog DNMT3L (72% identical), rat Dnmt3l (65% identical), mouse Dnmt3l (63% identical), guinea pig DNMT3L (61% identical), zebrafish dnmt3ba (35% identical), zebrafish dnmt3bb.3 (34% identical), zebrafish dnmt3bb.2 (33% identical). Paralogues in human: DNMT3A (40% identical), DNMT3B (37% identical), PWWP2B (11% identical), PWWP2A (10% identical).
Diseases named in the same sentence as DNMT3L in open-access papers:
DNMT3L is named in the same sentence as 46 diseases in open-access papers, as found by Europe PMC text mining. Sharing a sentence is not in itself a finding about the gene and the disease. The quoted sentences say what the papers report.
embryonal carcinoma (5 papers, 2013 to 2023). A non-seminomatous malignant germ cell tumor characterized by the presence of large germ cells with abundant cytoplasm resembling epithelial cells, geographic necrosis, high mitotic activity, and pseudoglandular and pseudopapillary structures formation. "This is the advantage of using SssI as a methylation effector in various types of cells including DNMT3L downregulated cells such as teratoma or some of the embryonal carcinoma-derived cell lines." (PMID 28542388, 2017). "During xenograft experiments, where seminoma-like TCam-2 cells transit to an embryonal carcinoma-like state DNMT3B and DNMT3L where strongly upregulated, which correlated to increasing 5-methylcytosine levels." (PMID 24386123, 2013). "An overexpressiοn of the DNMT3L protein has been shown in embryonal carcinoma but not in other types of testicular germ cell tumors." (PMID 37894317, 2023). "Interestingly, embryonal carcinomas display high levels of DNMT3B and DNMT3L." (PMID 23967156, 2013).
Down syndrome (4 papers, 2019 to 2021). "In contrast, the Down syndrome associated overexpression of DNMT3L in neural progenitor cells of frontal cortex could underlie one mechanistic cause of the consequential neural disorder." (PMID 32195249, 2020). "Overall, our findings suggest that DNMT3L overexpression during neuronal differentiation recreates a facet of the aberrant Down syndrome DNA methylation signature by targeting specific chromatin states that regulate genes important for neurodevelopment." (PMID 33750431, 2021). "These exons corresponded to 7 genes, 3 of which have been previously associated with Down syndrome: GART, DNMT3L and AIRE." (PMID 33081811, 2020).
male infertility (4 papers, 2012 to 2021). The inability of the male to effect fertilization of an ovum after a specified period of unprotected intercourse. "The purpose of this study was to investigate the association between male infertility and single-nucleotide polymorphisms (SNPs) of DNA methyltransferases (DNMT) genes (DNMT3B: rs2424909, DNMT1: rs4804490, DNMT3A: rs1550117 and DNMT3L: rs7354779)." (PMID 28894282, 2017). "In mouse, Dnmt3c and Dnmt3l mutants have similar meiotic phenotypes, including male infertility due to spermatocyte arrest apparently occurring at epithelial stage IV (and this study)." (PMID 28854222, 2017). "DNMT3L as well as PIWIL2 and TDRD1 null models revealed a loss of methylation at LINE-1 and intracisternal A-particle (IAP) transposons, leading to reactivation of repetitive elements that contribute to meiotic arrest and male infertility." (PMID 23112866, 2012). "Although DNMT3L does not have a catalytic subunit, it is an important co-activator of DNMT3a and B activity and Dnmt3l knockout has been shown to impair spermatogenesis and cause male infertility, a phenotype observed in F1." (PMID 34968297, 2021).
schizophrenia (4 papers, 2014 to 2022). A major psychotic disorder characterized by abnormalities in the perception or expression of reality. "Recently, it was reported that DNMT3B rs2424932 was strongly associated with gender and DNMT3B rs1569686 associated early age onset of schizophrenia while DNMT3L rs2070565 associated with family history and early onset of schizophrenia." (PMID 35832186, 2022). "Recently, a south Indian population was studied for genetic polymorphism in DNMT1, DNMT3A, DNMT3B, and DNMT3L for association with schizophrenia." (PMID 27314012, 2016). "We screened for polymorphisms in DNA methyltransferases, DNMT1, DNMT3A, DNMT3B and DNMT3L in 330 schizophrenia patients and 302 healthy controls for association with Schizophrenia in south Indian population." (PMID 24859147, 2014). "DNMT3L rs2070565 (genotype P = 0.007, allele P = 0.0026) confers an increased risk of developing schizophrenia at an early age in individuals with family history." (PMID 24859147, 2014). "The aim of the present study was to identify the role of genetic variants in DNA MethylTransferases such as maintenance methyltransferase gene (DNMT1) and genes for de novo methyltransferases (DNMT3A & 3B) and DNMT3L in predisposing to schizophrenia." (PMID 24859147, 2014). "Association analysis of DNMT1, DNMT3A, DNMT3B and DNMT3L polymorphisms are summarised by -Log P value for schizophrenia in a South Indian population." (PMID 24859147, 2014). "This suggests the role of DNMT3L rs2070565, in predisposing individuals with a positive family history with increased risk of developing Schizophrenia at an early age." (PMID 24859147, 2014). "In addition to the reports that related overexpression of DNMT1 in brain samples from schizophrenia patients, certain alleles of Dnmt1, Dnmt3A, and Dnmt3L have been found to be associated with schizophrenia." (PMID 26798355, 2016). "The genetic variants in DNMT1, rs2114724 and rs2228611, were found to be significantly associated with schizophrenia while de novo DNMTs variants, DNMT3B rs2424932, DNMT3B rs156968, and DNMT3L rs2070565, were associated with early age onset of disease." (PMID 27314012, 2016). "Observations from association analyses of SNPs in DNMT1, DNMT3A, DNMT3B, and DNMT3L indicated that DNMT1 rs2114724 and rs2228611 were strongly associated with schizophrenia at allelic and genotypic level." (PMID 24859147, 2014). "None of the selected SNPs in DNMT3B, and DNMT3L were found to be associated with schizophrenia." (PMID 24859147, 2014).
seminoma (4 papers, 2013 to 2016). A radiosensitive malignant germ cell tumor found in the testis (especially undescended), and extragonadal sites (anterior mediastinum and pineal gland). "Furthermore, additional EC and pluripotency genes were upregulated (SOX2, LEFTY1 /2, DNMT3L, SALL4, DPPA5, BCAT1, FZD7, LIN28, ZIC3), while seminoma-associated genes where downregulated (SOX17, TFAP2C, cKIT, PRAME), without changing 5mC-levels." (PMID 26226633, 2015).
gastric cancer (3 papers, 2019 to 2023). A primary or metastatic malignant neoplasm involving the stomach. "EGR1 may interact with DNMT3L, inhibit the miR-195-AKT3 axis, and regulate gastric cancer cell apoptosis." (PMID 36120336, 2022).
Infertility (3 papers, 2018 to 2021). "Loss of function of methyltransferase DNMT3L leads to infertility due to an “inappropriate euchromatin” state during meiosis, including transcriptional activation of retrotransposons." (PMID 34295895, 2021). "Mouse dnmt3l mutants also have altered DNA methylation and chromatin signatures and increased DSB initiation within retrotransposons, which is associated with meiotic catastrophe and infertility." (PMID 29530927, 2018). "Apart from infertility, Dnmt3l KO mice does not cause any other obvious defects." (PMID 33718357, 2021).
Obesity (3 papers, 2014 to 2018). Accumulation of substantial excess body fat. "The top gene, DNMT3L, is an enzymatically inactive regulatory factor, regulates DNA methylation activity, and is closely associated with epigenetic functions influencing obesity from epigenetic and regulation evidence." (PMID 30275894, 2018). "In addition, DNMT3L, which is known to regulate DNA methylation activity and is associated with obesity, was identified." (PMID 30255820, 2018). "Both gene-based and region-based tests implied that DNMT3L plays a crucial role in influencing the mechanism and effects of triglyceride-lowering drugs treating obesity." (PMID 30275894, 2018). "The roles of the top SNP, rs964184, and the top gene, DNMT3L, were also found in other studies on obesity and triglycerides." (PMID 30275894, 2018). "The roles of the top SNP, rs964181, and the top gene, DNMT3L, were also found in other published studies of obesity and triglyceride levels." (PMID 30275894, 2018).
Azoospermia (2 papers, 2016 to 2017). Absence of any measurable level of sperm,whereby spermatozoa cannot be observed even after centrifugation of the semen pellet. "The disruption of the Dnmt3L in testes resulted in a progressive loss of the spermatogonia, and further caused a complete azoospermia." (PMID 28881852, 2017). "Disruption of Dnmt3l caused azoospermia in homozygous males and heterozygous progeny of homozygous female died before midgestation." (PMID 27446199, 2016).
cervical cancer (2 papers, 2011 to 2014). A primary or metastatic malignant neoplasm involving the cervix. "Recently the loss of DNA methylation at the DNMT3L promoter was found to be a positive biomarker for cervical cancer." (PMID 21347319, 2011). "This study highlights the importance of DNA methylation profile at DNMT3L promoter as a promising biomarker for cervical cancer and provides insight into the possible role of DNMT3L in cancer development." (PMID 24822169, 2014). "Our findings with regard to DNMT3L methylation and KRAS mutation need to be investigated further as recently aberrant promoter hypomethylation of DNMT3L has been linked with cervical cancer tumorigenesis." (PMID 21347319, 2011). "DNMT3L over expression in cervical cancer cells increases cellular proliferation, anchorage independent growth and nuclear reprogramming of cells, all central events in tumour development." (PMID 21347319, 2011).
colon cancer (2 papers, 2019 to 2022). "Additionally, the expression of ARID1B was positively correlated with the expression of three methyl transferases (DNMT1, DNMT3A, and DNMT3L) in colon cancer, although the difference was not significant." (PMID 36313455, 2022).
alcohol abuse (1 paper, 2019). The use of alcoholic beverages to excess, either on individual occasions ("binge drinking") or as a regular practice. "Expression of DNMT1, DNMT3B and DNMT3L was identified to be negatively correlated with the expression of TNFRSF12A in 116 HCC with alcohol abuse (r <−0.22, p < 0.01)." (PMID 31998364, 2019). "The further mechanism analysis revealed that the DNA methyltransferases DNMT3L might regulate TNFRSF12A methylation and affect the occurrence, development and prognosis of HCC, especially in patients with a history of alcohol abuse." (PMID 31998364, 2019).
Alcoholism (1 paper, 2019). "Searching for DNMT3L in protein and protein interaction search tools (String) found that eight related proteins are enriched in the protein interaction network and related to KEGG pathway-Alcoholism." (PMID 31998364, 2019).
cervical tumors (1 paper, 2020). "The DNMT3L gene was also classified as a prognostic marker in cervical tumors and GCTs." (PMID 33473258, 2020).
depression (1 paper, 2020). "We suggested some important questions for the further exploration in this field, especially on DNMT3L, a little studied modulator of de novo DNA methylation during brain development, its expression relatively rich in hippocampus and amygdala, which are important brain areas for depression." (PMID 33101076, 2020). "This indicates DNMT3L may function differently compared with other DNMTs, important in neurogenesis and neural plasticity, which are essential processes during brain maturation, a stage when the prevalence of early-onset depression is high." (PMID 33101076, 2020). "The only report on DNMT3L expression in depression patients showed the expression of DNMT3L in blood samples of patients with depression was not significantly different from that of psychiatrically healthy controls." (PMID 33101076, 2020).
hepatocellular carcinoma (1 paper, 2024). A malignant tumor that arises from hepatocytes. "We examined the expression of DNMT3L in four human hepatoma cell lines and observed that it was relatively low in HCCLM3 and Hep3B." (PMID 38308276, 2024). "The effects of DNMT3L on the malignant phenotypes of hepatoma cells were confirmed in vitro and in vivo." (PMID 38308276, 2024). "To explore whether DNMT3L regulates the malignant cell phenotype of HCC through CDO1, we assessed whether inhibiting CDO1 could reverse the effects of DNMT3L overexpression on the biological behaviors of hepatoma cells." (PMID 38308276, 2024). "DNMT3L is a crucial DNA methylation regulatory factor, yet its function and mechanism in hepatocellular carcinoma (HCC) remain poorly understood." (PMID 38308276, 2024). "Initially, we evaluated the expression of CDO1 in four human hepatoma cell lines and found that HCCLM3 and Hep3B had relatively low CDO1 expression levels similar to DNMT3L." (PMID 38308276, 2024).
hypogonadism (1 paper, 2014). A disorder characterized by decreased function of the gonads. "Males carrying null alleles at Dnmt3l show phenotypes similar to those documented in F1s associated with the X-17 interaction, including hypogonadism, asynapsis during meiosis, abnormal formation of the sex body, and deregulation of X-linked and autosomal genes." (PMID 24586194, 2014).
lymphoma (1 paper, 2024). A malignant (clonal) proliferation of B- lymphocytes or T- lymphocytes which involves the lymph nodes, bone marrow and/or extranodal sites. "There are five members in the DNMT family, including DNMT1, DNMT2, DNMT3a, DNMT3b, and DNMT3L, the most common mutation of DNMT in cancer is the DNMT3a mutation, while DNMT3b is a pro-carcinogenic gene in endometrial, lung and prostate cancer, and a tumor suppressor gene (TSG) in lymphoma." (PMID 38200495, 2024).
mucinous carcinomas (1 paper, 2023). "Like serous carcinomas, mucinous carcinomas also displayed a higher expression of DNMT1 and DNMT3L in comparison with non-neoplastic tissues (p = 0.042 and p = 0.045, respectively)." (PMID 37894317, 2023).
neurofibromatosis type 1 (1 paper, 2019). A clinically heterogeneous, neurocutaneous genetic disorder characterized by cafe-au-lait spots, iris Lisch nodules, axillary and inguinal freckling, and multiple neurofibromas. "Most significant enrichment was observed for NF1 (P = 0.000477, OR = 22.8), the gene causal for neurofibromatosis type 1 (NF1), followed by TRPM5, AP5B1, DNMT3L and ARFGEF1." (PMID 31175295, 2019).
ocular cancer (1 paper, 2014). A benign or malignant neoplasm affecting the structures of the eye. "DNMT3L DMC is the same region which was shown to be hypomethylated in cervical and ocular cancer samples." (PMID 24743422, 2014).
osteoporosis (1 paper, 2021). A condition of reduced bone mass, with decreased cortical thickness and a decrease in the number and size of the trabeculae of cancellous bone (but normal chemical composition), resulting in increased fracture incidence. "Despite the serious osteogenesis impairment of Dnmt3l KO MSCs in vitro, counterintuitively, does not correlate to strong bone formation defects or osteoporosis phenotype in vivo." (PMID 33718357, 2021). "However, we did not observe the expected osteoporosis related symptoms in Dnmt3l KO aging female mice." (PMID 33718357, 2021).
ovarian carcinoma (1 paper, 2023). A malignant neoplasm originating from the surface ovarian epithelium. "Ιt should be noted that the expression of the DNMT2 and DNMT3L proteins in ovarian carcinomas by immunohistochemistry has not been reported in the literature before." (PMID 37894317, 2023).
ovarian tumors (1 paper, 2023). "Further study of the role of DNMT3L in de novo DNA methylation in ovarian tumors is warranted." (PMID 37894317, 2023).
Turner syndrome (1 paper, 2011). Turner syndrome is a chromosomal disorder associated with the complete or partial absence of an X chromosome. "Collectively, these data raise the possibility that decreased expression of DNMT3L in humans may also lead to Klinefelter's or Turner's syndromes in some children." (PMID 21483837, 2011). "Furthermore, these data raise the clinically important prospect that deregulated DNMT3L production may contribute to the aetiology of human Klinefelter's and Turner's syndromes." (PMID 21483837, 2011).